TBCAP1 (tubulin folding cofactor A pseudogene 1)
Gene: Processed pseudogene on chromosome X (33,041,395 to 33,041,721, forward strand). Ensembl gene ENSG00000226781.
Diseases named in the same sentence as TBCAP1 in open-access papers:
TBCAP1 is named in the same sentence as 1 disease in open-access papers, as found by Europe PMC text mining. Sharing a sentence is not in itself a finding about the gene and the disease.
TBCAP1 shares sentences with these, for which no sentence is quoted: neuroblastoma (1 paper).